ZNFX1 (zinc finger NFX1-type containing 1)
Diseases named in the same sentence as ZNFX1 in open-access papers:
ZNFX1 is named in the same sentence as 27 diseases in open-access papers, as found by Europe PMC text mining. Sharing a sentence is not in itself a finding about the gene and the disease. The quoted sentences say what the papers report.
viral infection (11 papers, 2020 to 2025). "G3BP2, a key component of stress granules, is implicated in viral infection, while ZNFX1 is essential for initiating the type I interferon (IFN) response." (PMID 40783707, 2025). "ZNFX1 deficiency predisposes to severe viral infections and an HLH-like multisystem inflammatory disease as a result of dysbalanced interferon production." (PMID 41300767, 2025). "The present study expands the role of ZNFX1 to include the regulation of infections caused by bacterial or fungal pathogens beyond viral infections." (PMID 39333773, 2024). "Recent clinical studies conducted by different research groups have highlighted the association of loss-of-function mutations in ZNFX1 with familial multisystem inflammatory disease and severe viral infections." (PMID 39333773, 2024). "As a consequence, mice deficient for ZNF1X show increased susceptibility to viral infection and those results have been recently confirmed in human with biallelic ZNFX1 deficiencies." (PMID 35087521, 2021). "Interestingly, deficiencies in ZNFX1 are also associated with uncontrolled inflammation following viral infection, in both humans and mice." (PMID 35087521, 2021). "During virus infection, ZNFX1 expression is upregulated and ZNFX1 bind to viral RNA, then induces MAVS-mediated antiviral innate immunity." (PMID 39547416, 2024). "In humans, homozygous ZNFX1 destabilizing pathogenic gene variants were associated with multisystem inflammation, including HLH, monocytosis, and a predisposition to viral infections and mycobacterial disease." (PMID 37187762, 2023). "As a consequence, patients with homozygous ZNFX1 destabilizing mutations suffered from multisystem inflammation, including HLH, and a predisposition to viral infections." (PMID 37187762, 2023). "We therefore propose a mechanism whereby the helicase function of ZNFX1 is needed to remove mRNAs which has been formed in consequence of a viral infection." (PMID 37187762, 2023). "Recently zinc finger NFX1-type containing 1 (ZNFX1) was identified as a long dsRNA sensor that functions to sense viral RNA during the early stages of viral infection." (PMID 32012730, 2020). "To date, the reported function of ZNFX1 has been restricted to ISG signaling, where the absence of ZNFX1 is associated with the extended half-life of ISGs and a loss of control over virus infection." (PMID 38016036, 2024). "In contrast, upon stimulation with dsRNA or dsDNA, primary cells from patients with autosomal recessive immunodeficiency carrying deleterious variants of ZNFX1 showed an extended half-life of ISG mRNA, unbalanced innate immune response, and decreased clearance of virus infection." (PMID 38016036, 2024). "In addition, two further helicases among the PoRs, DDX60L and ZNFX1, were recently described to be involved in the human innate immune response against viral infection." (PMID 32545414, 2020). "Additionally, ZNFX1 serves as a sensor for double-stranded nucleic acids during viral infection." (PMID 38016036, 2024). "Mammalian ZNFX1 suppresses NLRP3 inflammasome activation in lipopolysaccharide stimulated mice and accelerates the decay of IFN and ISGs mRNA during viral infection, thereby protecting cells from immune storms." (PMID 41160652, 2025). "The newly described ZNFX1 gene related to FHL and its tendency for viral infections was described in three cases in one family." (PMID 41300767, 2025). "However, whether ZNFX1 in lower vertebrates can function in viral infection remains unclear." (PMID 41160652, 2025). "ZNFX1 recognizes dsRNA and promotes type I IFN response in the early stage of viral infection, thereby enhancing antiviral immune effects." (PMID 38016036, 2024).
breast carcinoma (3 papers, 2016 to 2025). "ZFAS1 is a lncRNA transcribed antisense to the ZNFX1 protein-coding gene, first identified as an lncRNA involved in mammary development and subsequently found to have altered expression in breast cancer." (PMID 29701689, 2018). "Expression of ZFAS1 and ZNFX1 has been evaluated in breast epithelial and breast cancer cell lines using these new sets of primers showing nearly identical patterns of expression." (PMID 27871336, 2016). "Aside from a single report that ZNFX1 is upregulated in breast cancer cells following exposure to chemotherapeutic agents, the roles of ZNFX1 during development and human carcinogenesis remain unknown." (PMID 40211119, 2025).
gastric cancer (2 papers, 2019 to 2023). A primary or metastatic malignant neoplasm involving the stomach. "Zinc Finger NFX1-Type Containing 1 (ZFAS1) can forecast the clinical outcome of patients with different neoplasms including colorectal cancer, gastric cancer, and other types of cancer." (PMID 37302999, 2023). "ZNFX1 antisense RNA 1 (ZFAS1), a novel lncRNA transcribed in the antisense orientation of zinc finger NFX1‐type containing 1(ZNFX1), was found to be increased in multiple cancers, such as gastric cancer and hepatocellular carcinoma, contributing to cancer development and progression." (PMID 30288832, 2019).
COVID-19 (1 paper, 2025). A disease caused by infection with severe acute respiratory syndrome coronavirus 2. "Activation of ZNFX1 in immune cells isolated from bronchoalveolar lavage of patients with COVID-19 has been identified as an important component of the antiviral response." (PMID 40378209, 2025).
Hepatomegaly (1 paper, 2024). Abnormally increased size of the liver. "Multiple biallelic mutations in the ZNFX1 gene in humans have been associated with severe inherited immunodeficiency, such as MSMD, which presents with multiple clinical symptoms, including monocytosis, neutrophilia, thrombocytopenia, hepatomegaly, and splenomegaly." (PMID 38016036, 2024).
lung carcinoma (1 paper, 2025). "Our experiments also demonstrated that overexpression of ZNFX1 represses growth of lung tumor cells in vitro and in vivo; these observations suggest that ZNFX1 encodes a novel tumor suppressor that is inactivated in lung cancers." (PMID 40211119, 2025). "Among diverse alterations of lncRNA and coding gene expression profiles in NREC exposed to CSC, we observed upregulation of lncRNA ZFAS1 and repression of an adjacent protein-coding gene, ZNFX1, and confirmed these findings in primary lung cancers." (PMID 40211119, 2025). "Phenotypic experiments indicated that ZFAS1 is an oncogene, whereas ZNFX1 functions as a tumor suppressor in lung cancer cells." (PMID 40211119, 2025). "In contrast, ZNFX1 mRNA levels were lower (mean 7.4-fold; range 6.4–12.1-fold) in lung cancers relative to paired normal lung tissues (p < 0.01)." (PMID 40211119, 2025). "Methysticin, a naturally occurring inhibitor of NFkB signaling, repressed ZFAS1 while simultaneously upregulating ZNFX1 in a dose-dependent manner in cultured A549 lung cancer cells." (PMID 40211119, 2025). "We conducted quantitative chromatin immunoprecipitation (qChIP) experiments to further investigate epigenetic mechanisms regulating ZNFX1 expression in normal respiratoy epithelial cells and lung cancer cells." (PMID 40211119, 2025). "We next investigated the impact of ZNFX1 expression on the in vivo growth of lung cancer cells." (PMID 40211119, 2025). "Despite these limitations, our findings that SP1 and NFĸB inhibitors simultaneously repress ZFAS1 and restore ZNFX1 expression in lung cancer cells provide proof of concept that ZFAS1–ZNFX1 dysregulation during pulmonary carcinogenesis is potentially druggable in the clinic." (PMID 40211119, 2025). "qRT-PCR experiments demonstrated that 5-aza-2′ deoxycytidine (DAC);100 nM for 72 h), upregulated ZNFX1 in lung tumor cells while markedly abrogating CSC or ZFAS1 overexpression-mediated ZNFX1 repression in NREC and lung cancer cells." (PMID 40211119, 2025). "Given the limited smoking-related lung cancer specimens for analysis of the inverse correlation of ZFAS1 and ZNFX1 and the complexity of cell populations of these specimens, we performed additional correlation analysis using publicly accessible scRNA datasets." (PMID 40211119, 2025). "In contrast, knockdown of ZNFX1 modestly enhanced proliferation of SAEC and HBEC; even though endogenous levels of ZNFX1 expression were quite low in lung cancer lines, knockdown of ZNFX1 enhanced growth of lung cancer cells." (PMID 40211119, 2025). "Immunoblot experiments confirmed that ZFAS1 overexpression decreased ZNFX1 protein levels in SAEC and HBEC; this phenomenon could not be demonstrated in lung cancer cells owing to very low levels of ZNFX1 in control cells (data not shown)." (PMID 40211119, 2025).
melanoma (1 paper, 2020). A malignant, usually aggressive tumor composed of atypical, neoplastic melanocytes. "It is very likely that the knockdown of ZNFX1 resulted in the proportional increase in the levels of its antisense, thus, explaining the respective increase in melanoma cell migration." (PMID 33041669, 2020). "Here we present the results of transient siRNA-mediated knockdown of the four of such genes, namely, UNC45A, STK11IP, RHPN2 and ZNFX1, in melanoma cell line A375, then assayed the cells for their viability, proliferation and ability to migrate in vitro." (PMID 33041669, 2020). "For each of the genes, namely ZNFx1, RHPN2, STK11IP and UNC45A, from 1 to 3 siRNAs were designed and tested in melanoma cell line A375." (PMID 33041669, 2020).
tuberculosis (1 paper, 2024). A chronic, recurrent infection caused by the bacterium Mycobacterium tuberculosis. "Individuals with deficiencies in ZNFX1 have been proposed to suffer more from TB than from MSMD, as the virulence of M. tuberculosis is approximately 1,000 times greater than that of BCG." (PMID 38016036, 2024). "This suggested a potential role for ZNFX1 in the development of M. tuberculosis–induced TB." (PMID 38016036, 2024).
typhoid fever (1 paper, 2023). A bacterial infectious disorder contracted by consumption of food or drink contaminated with Salmonella typhi. "Furthermore, an investigation is required to characterize the similar inborn single nucleotide mutations in genes to those discussed here (IL-23R and ZNFX1), which caused recurrent typhoid fever." (PMID 36845636, 2023).
uveitis (1 paper, 2025). An inflammatory process affecting a part of or the entire uvea. "For instance, in the uveitis only group, the genes KLHL21, MYLIP, ZNFX1, PDE4A, TNFRSF21, and N4BP2L2 were downregulated, while METTL72, GAPT, CD180, CCR2, and TLR7 were upregulated when comparing uveitis patients with healthy controls." (PMID 40270958, 2025).
infection (8 papers, 2022 to 2026). The state of being infected such as from the introduction of a foreign agent such as serum, vaccine, antigenic substance or organism. "The expression of Prkaa2 increased following H37Rv infection, indicating its close association with the response to M. tuberculosis infection and implicating AMPKα2 in mediating the functions of ZNFX1." (PMID 38016036, 2024). "Patients from two unrelated families who carry homozygous ZNFX1 variants have been reported to exhibit mycobacterial disease alongside intermittent monocytosis, which is a condition characterized by temporary increases in monocytes and likely to be indicative of infection." (PMID 40170857, 2025). "Consistent with ZNFX1 contributing to proper regulation of immune responses, ZNFX1 is induced by infections in many species." (PMID 40170857, 2025). "Similar to previous reports, the expression levels of IFIT1, IRF1, and MX1 in Znfx1–/– BMDMs were higher than those in WT BMDMs following H37Rv infection, despite the increased intracellular M. tuberculosis burden in Znfx1–/– BMDMs." (PMID 38016036, 2024). "As an ISG, ZNFX1 is rapidly upregulated together with NLRP3 during the early stages of infection, keeping NLRP3 in check." (PMID 39333773, 2024). "MiR29b-1* mimic transfection significantly reduced AdV-C5 infection in siRNA-treated cells, despite efficient ZNFX1 knockdown." (PMID 35891387, 2022). "ZNFX1 might be involved in different aspects of immunoregulation throughout the stages of an infection." (PMID 40170857, 2025). "Given the similarity in NFX1-type zinc fingers between NFX1 and ZNFX1, it is plausible that zinc finger regions of ZNFX1 could mediate host RNA expression following an infection." (PMID 40170857, 2025). "At later stages of an infection or when an infection is cleared, ZNFX1 could function to balance inflammatory signals and prevent persistent inflammation." (PMID 40170857, 2025). "In addition, 80% of Znfx1-/- mice infected with VSV demonstrated conjunctivitis one day post infection, and their lungs showed more infiltration by inflammatory cells compared to controls." (PMID 40170857, 2025). "This suggests that either an initial infection is never fully cleared in the absence of ZNFX1 or ZNFX1 deficiency causes dysregulation in the immune response that prevents cells from returning to normal homeostasis after the infection is cleared." (PMID 40170857, 2025). "ZNFX1 patient-derived monocytes were shown to be less efficient in clearing virus compared to controls after being subjected to poly(I:C) pre-stimulation and infection with VSV in vitro." (PMID 40170857, 2025). "Furthermore, AMPK activation contributed to injury repair in lung tissues, compromised inflammatory infiltration, and suppressed CI, as indicated by the splenic MGCs resulting from Znfx1 knockout after H37Rv infection." (PMID 38016036, 2024). "In the early stages of an infection, ZNFX1 could serve to promote viral clearance." (PMID 40170857, 2025). "In the peripheral blood of ZNFX1-deficient patients who do not have any known ongoing infections, many interferon-stimulated genes (ISGs) involved in antiviral and PAMP sensing such as OAS1/2, IFIT2/3 and IRF7 were detected at a higher level compared to healthy controls." (PMID 40170857, 2025). "qPCR and Western blot analysis validated that the absence of ZNFX1 led to a significant downregulation of Prkaa2, irrespective of H37Rv infection." (PMID 38016036, 2024). "However, co-IP detection did not support the association between ZNFX1 and AMPKα2 or LKB1 in BMDMs, regardless of H37Rv infection." (PMID 38016036, 2024). "However, ZNFX1 did not appear to affect IL-4 and IL-10 expression in the early stages of infection." (PMID 38016036, 2024). "Znfx1–/– BMDMs expressed significantly reduced levels of CD80, CD86, and MHC-II in response to H37Rv infection, without influencing the expression of CD206, a marker of type II macrophages." (PMID 38016036, 2024).
infection (continued). "We also examined IFN-stimulated proteins whose induction was suppressed by infection, but not by heat-inactivated virions or upon inhibition of viral DNA replication (ISG20, OASL, ZNFX1)." (PMID 38065956, 2023). "The inhibition of AdV-C5 infection with miR-29b-1* mimic depended on the IFN-alpha receptor 2 (IFNAR2) and the RNA-helicase retinoic acid-inducible gene I (RIG-I) but not cytoplasmic RNA sensors MDA5 and ZNFX1 or MyD88/TRIF adaptors." (PMID 35891387, 2022).
cancer (7 papers, 2019 to 2025). A tumor composed of atypical neoplastic, often pleomorphic cells that invade other tissues. "Among cancer cell lines of diverse histologies in this database, ZNFX1 mRNA levels appear to be decreased in NSCLC and are considerably low in SCLC, which typically arise in individuals with extensive smoking histories and exhibit high mutational burden." (PMID 40211119, 2025). "The significant differences between expression levels of ZNFX1 were observed in the case of gender (p = 0.0004), cancer stage (p < 0.0001) and T-stage (p = 0.0240), cancer grade (p = 0.0158), perineural invasion (p = 0.0022) or HPV status (p = 0.0086)." (PMID 31010087, 2019). "The expression of ZNFX1 was significantly up-regulated in cancer samples of HNSCC patients compared to normal tissue (median expression of 19.823 vs. 9.783 transcripts per million; p = 1.62 × 10−12)." (PMID 31010087, 2019). "Next, the expression levels of ZNFX1 were checked depending on cancer localization." (PMID 31010087, 2019). "Located in the antisense strand adjacent to the 5′ end of the Zinc Finger NFX1-Type Containing 1 coding gene (Znfx1), Znfx1 antisense RNA (ZFAS1) has been proposed as an oncogenic lncRNA in almost all types of human malignant tumors." (PMID 37534277, 2023). "Unfortunately, there is lack of reports indicated the role of ZNFX1 in HNSCC or other cancers." (PMID 31010087, 2019). "Some of them were previously demonstrated to play a role in other cancers (UNC45A, STK11IP), and some were not yet characterized (RHPN2 and ZNFX1)." (PMID 33041669, 2020).
bacterial infections (1 paper, 2025). "On OAR13:77,378,009 was found the SNP rs416157010, which was found to be associated with TNB, and in this region is the ZNFX1 (zinc finger NFX1-type containing 1) gene, a component of the regulation of the telomerase pathway, and is required against some bacterial infections." (PMID 40678382, 2025).
ZNFX1 also shares sentences with these, for which no sentence is quoted: neoplasm (2 papers); breast tumors (1); chronic granulomatous disease (1); colorectal cancer (1); Hemophagocytic Lymphohistiocytosis (1); hepatocellular carcinoma (1); Immunodeficiency (1); influenza infection (1); Mendelian susceptibility to mycobacterial diseases (1); sarcoma (1); Sepsis (1); Splenomegaly (1); Thrombocytopenia (1); Wolman disease (1).